CTSK (cathepsin K)
Description:
Thiol protease involved in osteoclastic bone resorption and may participate partially in the disorder of bone remodeling. Displays potent endoprotease activity against fibrinogen at acid pH. May play an important role in extracellular matrix degradation. Involved in the release of thyroid hormone thyroxine (T4) by limited proteolysis of TG/thyroglobulin in the thyroid follicle lumen.
Synonyms: CTSO; CTSO2; PKND; CTS02; CTSO1; PYCD
Tractability: Small molecule: a drug acting on it is in phase 2 or 3 trials; a structure with a bound ligand is known; a high-quality ligand is known; it has a high-quality binding pocket; it belongs to a druggable protein family. Antibody: UniProt places it where antibodies can reach, with high confidence; its Gene Ontology location is reachable by antibodies, with high confidence; UniProt predicts a signal peptide or a membrane-spanning region. PROTAC: a small molecule that binds it is known. Other modalities: a drug acting on it is in phase 2 or 3 trials.
Target class: Cysteine protease; Cysteine protease CA clan; Enzyme; Protease; Cysteine protease C1A family
Chemical probes: L-006235, L-873724, MG-132, PD059579, PD080728, PD080775, PD080803, PD080869, PD080941, PD081405, PD081526, PD081564, PD081753, PD081927, PD082107, PD082141, PD082405, PD082634, PD082682, PD083093, and 16 more
Gene: Protein-coding gene on chromosome 1 (150,794,880 to 150,809,577, reverse strand). Ensembl gene ENSG00000143387.
Subcellular location: Lysosome; Secreted; Apical cell membrane
Subcellular location (Human Protein Atlas): Vesicles
Pathways (Reactome):
Extracellular matrix organization: Activation of Matrix Metalloproteinases; Collagen degradation; Degradation of the extracellular matrix
Immune System: MHC class II antigen presentation; Trafficking and processing of endosomal TLR
Gene expression (Transcription): RUNX1 regulates transcription of genes involved in differentiation of keratinocytes
Gene Ontology:
Molecular function: collagen binding; cysteine-type endopeptidase activity; cysteine-type peptidase activity; fibronectin binding; protein binding; proteoglycan binding; serine-type endopeptidase activity; peptidase activity
Biological process: collagen catabolic process; mitophagy; protein catabolic process; thyroid hormone generation; extracellular matrix disassembly; proteolysis
Cellular component: apical plasma membrane; extracellular region; lysosome; endolysosome lumen; lysosomal lumen; external side of plasma membrane
Genetic constraint (gnomAD): Loss-of-function variants: 18 observed, 35.68 expected, observed/expected ratio (o/e) 0.5, 90% interval 0.35 to 0.75. The upper end of that interval is the gene's LOEUF score, 0.75, which puts it in group 3 of 6, group 1 being the genes least tolerant of losing a copy. Missense variants: 271 observed, 387.75 expected, observed/expected ratio (o/e) 0.7, 90% interval 0.63 to 0.77. Synonymous variants: 124 observed, 142.16 expected, observed/expected ratio (o/e) 0.87, 90% interval 0.75 to 1.01.
Gene-disease validity (ClinGen):
ClinGen rates the evidence that CTSK causes each of these diseases.
pycnodysostosis (autosomal recessive): Definitive. Pycnodysostosis is a genetic lysosomal disease characterized by short stature, increased density of the bones (osteosclerosis/osteopetrosis), and brittle bones.
Homologues: Orthologues: chimpanzee CTSK (97% identical), pig CTSK (96% identical), dog CTSK (95% identical), rabbit CTSK (94% identical), guinea pig CTSK (94% identical), mouse Ctsk (86% identical), rat Ctsk (82% identical), tropical clawed frog ctsk.2 (71% identical), zebrafish ctsk (62% identical), Caenorhabditis elegans R09F10.1 (30% identical), Caenorhabditis elegans Y71H2AR.2 (28% identical), Caenorhabditis elegans Y113G7B.15 (27% identical), and 10 more. Paralogues in human: CTSS (55% identical), CTSL (51% identical), CTSV (51% identical), CTSH (41% identical), CTSF (31% identical), CTSW (28% identical), CTSO (28% identical), CTSC (27% identical), CTSB (24% identical), CTSZ (22% identical), TINAG (21% identical), TINAGL1 (21% identical).
Diseases named in the same sentence as CTSK in open-access papers:
CTSK is named in the same sentence as 238 diseases in open-access papers, as found by Europe PMC text mining. Sharing a sentence is not in itself a finding about the gene and the disease. The quoted sentences say what the papers report.
osteoporosis (137 papers, 2005 to 2026). A condition of reduced bone mass, with decreased cortical thickness and a decrease in the number and size of the trabeculae of cancellous bone (but normal chemical composition), resulting in increased fracture incidence. "CTSK encodes the Cathepsin K enzyme, which is expressed in OC for collagen degradation and its inhibition has become one target of osteoporosis and osteoarthritis treatment." (PMID 40565238, 2025). "Inhibitors of cathepsin K are in development for treatment of osteoporosis and have recently been shown to reduce fracture risk in patients with osteoporosis." (PMID 40200363, 2025). "CTSK is essential for normal bone remodeling, and its dysregulation is linked to bone disorders such as osteoporosis and pycnodysostosis." (PMID 40362457, 2025). "A phase three trial has shown that long-term treatment with a cathepsin K inhibitor, namely, odanacatib, significantly reduces osteoporosis and the risk of bone fracture in postmenopausal woman." (PMID 41357757, 2025). "Due to the essential role of CtsK in bone resorption, CtsK has been pursued as an attractive antiresorptive drug target in treating diseases associated with excessive bone resorption, such as osteoporosis, rheumatoid arthritis and periodontitis." (PMID 38260317, 2024). "In one study, the recombinant adeno-associated virus serotype 9 (rAAV9) was employed to deliver an artificial miRNA designed to silence the expression of a crucial OC regulator, CTSK (rAAV9.amiR-ctsk), aiming to prevent bone loss in osteoporosis." (PMID 39392536, 2024). "The results have suggested that delivery of CTSK-CeNP-siRNA by ultrasound-responsive NBs can be an effective treatment for osteoporosis and associated bone fractures." (PMID 38255196, 2024). "Cathepsin K has been found to be closely associated with osteoporosis and is currently one of the most attractive targets for osteoporosis therapy." (PMID 36662065, 2022). "The mechanisms of inhibition were via suppression of osteoporosis-related protein expression (NFATc1 and c-Fos), gene expression (Nfatc1, Ca2, Acp5, mmp9, CtsK, Oscar, and Atp6v0d2), and inhibited bone loss induced in the OVX model." (PMID 33859705, 2021). "Pathological collagen degradation is connected with cathepsin K overexpression and unbalanced osteoclast/osteoblast activation, leading to collagen I degradation and bone loss as seen in osteoporosis." (PMID 30897858, 2019). "Inhibitors of cathepsin K are in development for treatment of osteoporosis and have recently been show to reduce fracture risk in patients with osteoporosis." (PMID 27108405, 2016). "Cathepsin K is a lysosomal cysteine protease that is highly expressed on osteoclasts and has been implicated in the pathogenesis of osteoporosis and other bone diseases." (PMID 25692548, 2015). "Cathepsin K has thus been associated with OA, rheumatoid arthritis (RA) and osteoporosis pathogenesis." (PMID 25889265, 2015). "We plan to use this study as a foundation to design a new class of CtsK inhibitor, which can be further developed into an anti-resorptive therapeutics to curb undesired bone resorption in diseases like osteoporosis, periodontal bone loss, rheumatoid arthritis, Paget’s disease and cancer." (PMID 38260317, 2024). "On the other hand, cathepsin K hyperactivity has been linked to osteoporosis." (PMID 27375486, 2016). "Basically, deficiency in cathepsin K in humans and animals reflected a central role of this protease in bone resorption and, thus, have rendered the enzyme as a novel therapeutic target for treating osteoporosis and other disorders that are characterized by an elevation in bone resorption." (PMID 35883807, 2022). "Rare disorders associated with impaired osteoclastic bone resorption may also have utility in treating osteoporosis, exemplified by pycnodysostosis caused by cathepsin K deficiency, for which the inhibitor Odanocatib was developed as a new anti-resorptive treatment for osteoporosis." (PMID 33658983, 2020).
osteoporosis (continued). "Cathepsin K (CTSK), a proteolytic enzyme that degradesthe extracellularmatrix, is recognized as a significant therapeutic target for osteoporosis,osteoarthritis, and rheumatoid arthritis." (PMID 40151260, 2025). "Cathepsin K is involved in osteoclastic resorption, and considered a potential target for osteoporosis treatment." (PMID 41024853, 2025). "Odanacatib, an inhibitor of the main collagenase in osteoclasts, cathepsin K, was initially considered a revolution in osteoporosis therapy because the pharmacological mechanism differs from that of bisphosphonates and other antiresorptive agents." (PMID 40908780, 2025). "The molecular interactions of the components with Cathepsin K (CatK), which is used as a target in drug development against osteoporosis, were revealed by in silico molecular docking and MD methods." (PMID 39188072, 2025). "Given its pivotal role in the initial stages of bone resorption, cathepsin K has emerged as a therapeutic target in osteoporosis." (PMID 39947684, 2025). "Cathepsin K serves as a key activation marker for osteoclasts and is a therapeutic target in osteoporosis." (PMID 39940432, 2025). "Inappropriate upregulation of cathepsin K has been suggested in some bone disorders, including osteoporosis or PD." (PMID 41357757, 2025). "The enzyme analysis results of all these studies revealed that MMP2, MMP9, TIMP1, and TIMP2 were low and cathepsin K was high in MPS III patients, and that the patients had low bone density and increased osteoporosis risk." (PMID 40104299, 2025). "Odanacatib (ODN), a highly selective CTSK inhibitor, showed promise in clinical trials for osteoporosis." (PMID 39392536, 2024). "Cathepsin K plays a pivotal role in bone resorption and has emerged as a prominent therapeutic target for treating bone-related diseases such as osteoporosis." (PMID 39795149, 2024). "MST1 and MST2 strongly suppress the expression of CTSK that is highly produced in osteoclasts, the bone macrophages, and have been a therapeutic target for treating osteoporosis." (PMID 38624208, 2024). "Cathepsin K (CatK), an essential collagenase in osteoclasts (OCs), is a potential therapeutic target for the treatment of osteoporosis." (PMID 38548807, 2024). "This bone-targeted rAAV9-mediated silencing of CTSK and effectively inhibited OC-mediated bone resorption, presenting a promising strategy for the treatment of osteoporosis." (PMID 39392536, 2024). "Phytochemicals provide an untapped resource for developing therapeutics to address Cathepsin K-mediated diseases such as osteoporosis, arthritis, and other conditions involving pathological bone resorption." (PMID 39795149, 2024). "Although preclinical investigations have established a strong correlation between cathepsin K and the occurrence of bone metastases, clinical trials have predominantly prioritized the use of cathepsin K inhibitors for treating osteoporosis and arthritis." (PMID 39148909, 2024). "Cathepsin K inhibitors have gained significant attention as potential therapeutic agents for the treatment of osteoporosis and other bone-related disorders due to their ability to selectively target the collagen-degrading activity of osteoclasts." (PMID 39795149, 2024). "Suppression of OC’s bone resorptive activity with retaining OC viability has been demonstrated to efficiently increase bone formation in patients with osteoporosis under treatment with cathepsin K inhibitors." (PMID 37039914, 2023). "The cathepsin K inhibitor odanacatib inhibits bone resorption significantly and has once been considered a promising treatment for osteoporosis." (PMID 37188325, 2023). "Nanobubble gene delivery has been used for treating lung cancer and melanoma, but it can also be used for treating osteoporosis by encapsulating CTSK siRNA." (PMID 37896153, 2023). "Recently developed potent cathepsin K inhibitors act as useful anti-resorptive agents to treat osteoporosis." (PMID 36674719, 2023).
osteoporosis (continued). "The transcript levels of UBAP2 were significantly downregulated, while those of ACP5 and CTSK were upregulated in bone marrow samples from patients with osteoporosis compared with those in controls." (PMID 37339951, 2023). "Cathepsin K has long been regarded as a potential target for the treatment of diseases such as osteoporosis." (PMID 37334378, 2023). "One study demonstrated how the US-directed nanodroplets, embedded with alendronate and encapsulated with osteoporosis-related silencing gene Cathepsin K small interfering RNA (CTSK-siRNA-ND-AL), successfully suppressed osteoclastogenesis." (PMID 37504868, 2023). "The aim of this study was to investigate the effect of loading and releasing a mixture of CTSK siRNA and CeNPs from NB in vitro to evaluate their potential for use in osteoporosis treatment strategies." (PMID 37896153, 2023). "At present, an increasing number of medicines aiming at inhibiting the excessive formation of OCs have been used to treat osteoporosis, such as cathepsin K inhibitors and alendronate." (PMID 37464262, 2023). "For example, the selective inhibition of cathepsin K is thought to be beneficial for the treatment of osteoporosis, bone cancers, and certain forms of arthritis, based on the cathepsin K overexpression associated with these diseases." (PMID 36979788, 2023). "Cathepsin K is highly expressed in osteoclasts, and its inhibitors have been developed for osteoporosis management." (PMID 35164658, 2022). "Odanacatib developed by Merck & Co. is the only small molecular CTSK inhibitor candidate which demonstrated high therapeutic efficacy to increase bone mineral density in patients with osteoporosis." (PMID 36386169, 2022). "Owing to its prominent role in bone resorption, CTSK has become a therapeutic target for osteoporosis." (PMID 36005209, 2022). "Odanacatib is a selective inhibitor of CTSK which is served as the most promising drug for osteoporosis, it also effectively prevents the occurrence of periodontitis." (PMID 36386169, 2022). "This information suggests that NFATC1, cSRC, MMP-9 and Cathepsin K were the four core indicators of osteoclastogenesis involved in osteoporosis." (PMID 36431913, 2022). "CTSK is commonly highly expressed in osteoclasts of bone and would be upregulated under osteoporosis or rheumatoid arthritis; moreover, CTSK overexpression is also found in other tissue lesions, such as malignant cancers and heart failure." (PMID 36005209, 2022). "As CTSK bears the most potent protease activity in mediating bone resorption, it has become the most attractive target for anti-osteoporosis drug development." (PMID 33445732, 2021). "Cathepsin K has gained increased interest due to its role in bone resorption and is considered a novel target for osteoporosis treatment." (PMID 34205111, 2021). "Cathepsin K is primarily responsible for bone matrix degradation by osteoclasts and is currently the most attractive target for treating osteoporosis." (PMID 33748100, 2021). "The increase in bone density created significant scientific interest in targeting the enzymatic activity of the CTSK gene to increase bone density in patients with osteoporosis." (PMID 34680947, 2021). "Alternatively, during bone resorption as in osteoporosis, osteoclast markers cathepsin K and TRAP can be found in the circulation." (PMID 34721292, 2021). "The higher production of these proteins during osteoporosis is reflected in the finding that postmenopausal women with osteoporosis have higher circulating levels of cathepsin K." (PMID 34721292, 2021). "In particular, Cathepsin K expression is higher in breast cancer and tumor invasiveness in bones, as it is involved also in osteoporosis." (PMID 35723387, 2021). "Actually, there are 11 cathepsins encoded in the human genome – B, H, L, S, C, K, O, F, V, X e W; among them, cathepsin K has a key role in bone resorption and is closely related to bone diseases as osteoporosis." (PMID 33751248, 2021).